TIA1 (TIA1 cytotoxic granule associated RNA binding protein)
Diseases named in the same sentence as TIA1 in open-access papers (continued):
Sharing a sentence is not in itself a finding about the gene and the disease.
tumor (continued). "We also compared the expression level of these SFs in GBM tumor tissues and adjacent normal tissues and found that 7 factors were significantly dysregulated, including HNRNPA1, HNRNPC, HNRPLL, NOVA1, SF3B1, KHDRBS2, and TIA1." (PMID 34326872, 2021). "Tumor cells were all immunoreactive for CD3, granzyme B, and TIA-1; variable for CD56 (69.2%)." (PMID 34072328, 2021). "In the first case, tumour cells are negative for granzyme B and perforin but they express weakly TIA-1." (PMID 30151671, 2018). "PDCD4, an important tumor suppressor in CRC, has been reported to be regulated by TIA1." (PMID 28257633, 2017). "Furthermore, we revealed the important effects of miR-19a-driven suppression of TIA1 on the promotion of CRC cell proliferation and migration and on tumor growth in a xenografted nude mouse model." (PMID 28257633, 2017). "A staining pattern for TIA1 and TIAR was detected in the cytoplasm in non-tumor lung cells." (PMID 25741594, 2015). "First, to compare the profiles of tumor-infiltrating cytotoxic T lymphocytes between invasive and noninvasive EMPD, we employed immunohistochemical staining for CD8, granulysin, TIA-1, and perforin." (PMID 23606867, 2013). "We have further shown that the clinical benefit of adjuvant anthracycline-based therapy may be restricted to patients with high numbers of tumor-infiltrating T-cells, especially those of the CD8+ and TIA-1+ subsets." (PMID 22151962, 2011). "Given that TIA-1 is hypothesized as a marker for activated CD8+ T-cells, we verified the coexpression of TIA-1 on CD8+ T cells by flow cytometry on tumor infiltrating lymphocytes (TILs) from 10 freshly excised clinical specimens." (PMID 21179245, 2010). "In high-grade serous tumors from optimally debulked patients, positive associations were seen between intraepithelial cells expressing CD3, CD4, CD8, CD45RO, CD25, TIA-1, Granzyme B, FoxP3, CD20, and CD68, as well as expression of MHC class I and II by tumor cells." (PMID 19641607, 2009). "For both markers, there were either few or no infiltrates at all within the tumor epithelium (data not shown), indicating that the TIA-1+ and Granzyme B+ infiltrates were most likely T cells." (PMID 19641607, 2009). "However, the CD8+ T cell infiltrate was largely negative for both Granzyme B and TIA-1, suggesting these T cells were not capable of effective tumor lysis." (PMID 33603731, 2021). "Therefore, the oncogenic activities of TIA1 we found are not inconsistent with previous reports demonstrating that TIA1 works as a tumor suppressor." (PMID 26958940, 2016). "Finally, analysis of polysomal RNAs from livers of CTL and TIA1 knockdown LPTENKO mice indicated that consistent with a lack of effect of TIA1 downregulation on tumor growth and progression, markers for proliferation (Mki67, Pcna, Cdkn1a, Cdkn1b, Cdc25a) and inflammation (Il1b, Tgfb) were unchanged." (PMID 35406476, 2022). "Immunohistochemically, tumor cells are usually positive for CD3, CD8, CD56, TIA-1, granzyme B, and perforin, and negative for CD4 and CD5, consistent with the findings in our patient." (PMID 41328359, 2026). "Immunohistochemical staining showed strong expression of CD20, CD79a, and PAX5 in tumor cells, but CD3, CD56, and TIA1 were not expressed in tumor cells." (PMID 41291370, 2025). "The tumor showed strong expression of CD20, CD79a, PAX5, and Ki-67 (close to 90%), but CD3, CD56, and TIA1 were all negative." (PMID 41291370, 2025). "FC did not correlate with any of the markers of local tumour inflammation (Klintrup–Mäkinen grade, lymphocytes, neutrophils, CD3, CD4, CD8, CD45, TIA-1, granzyme B and myeloperoxidase)." (PMID 35397505, 2022).
tumor (continued). "Tumor cells were positive for CD3, CD8 (72.7%), CD56, CD103 (60%), granzyme B (81.8%), and TIA-1 (66.7%), while negative for CD20, CD10, PD-1, ALK, and EBER ISH." (PMID 34072328, 2021). "The tumour tissues in YT F0, YT F5 and YT F7were positive for CD56, Granzyme B, Perforin but negative for TiA1." (PMID 30484952, 2019). "The neoplasm tumor cells exhibit positive CD4, CD56 and CD123 expression, but are negative for CD3, TIA-1 and EBV expression." (PMID 25289105, 2014). "Immunohistochemically, the tumor cells tend to express CD56, cytoplasmic CD3ε, CD2, cytotoxic granule proteins, granzyme B, and TIA-1 but not surface CD3." (PMID 23958352, 2013). "Immunohistochemical examination revealed that the tumour cells expressed T-cell receptor (TCR)-βF1, CD3, CD4, CD25, cytotoxic-related protein TIA1 and granzyme-B, but were negative for CD8, Foxp3, CD20, CD30 and CD56." (PMID 23302373, 2013). "Immunohistochemically, the tumor cells were strong positive for CD56, CD3ε, TIA1, and weak positive for LMP1, and negative for CD5, CD8, CD20, CD79a, CgA, Syn, SCLC, CK, EMA, CD99, CD10, TdT, PAX-5, and BCL-6." (PMID 23958352, 2013). "Considering the findings of TIA-1+, EBER1+ and no TCR rearrangement, histological type of the tumor was finally diagnosed as CD56-negative extranodal NK/T-cell lymphoma (nasal type)." (PMID 22931631, 2012). "Immunohistochemically, the staining results of tumor cells in the small intestine and kidney were consistent; the tumor cells were positive for CD3, CD56, granzyme B, TIA-1, and perforin, while negative for CD4, CD8, CD5, Desmin, CD34, CKpan, CD20, CD30, SMA, CD79ɑ, and PAX8." (PMID 36199094, 2022).
cancer (35 papers, 2008 to 2025). A tumor composed of atypical neoplastic, often pleomorphic cells that invade other tissues. "Accordingly, TIA1 expression is frequently downregulated in human cancers and its loss correlates with a poor prognosis." (PMID 34502337, 2021). "Pathways associated with cancer are also enriched in the C+/+/Tia1−/− testis, and the genes Psrc1, Ano3 and Zfp365, all upregulated in C+/+/Tia1−/− testis, are regulated by the tumor suppressor p5368–70." (PMID 28775379, 2017). "Of the many RBPs that bind to the KRAS 3′ UTR, AGO2, HuR (or ELAVL1), IGF2BP1/2/3, PUM2, EWSR1, TAF15, FUS, and TIA1 have been previously implicated in cancer." (PMID 26930719, 2016). "Among patients with CD8-positive tumors, TIA-1 positivity led to a relative risk of 0.79 (95%CI: 0.7-0.9) compared to patients with TIA-1-negative cancers (p = 0.006)." (PMID 21179245, 2010). "Since SKP2 and CCNA2 are known to be implicated in the pathogenesis of various cancers as oncogenes, the effects of each TIA1 protein isoform on the SKP2 and CCNA2 protein levels were investigated using cells transiently expressing each isoform via retroviral infection." (PMID 26958940, 2016). "TIAR was more involved in several types of cancer, whereas TIA1, although also involved in kidney cancer, had more varied effects." (PMID 38534464, 2024). "Intriguingly, our analysis identified proteins known as main stress granule markers (G3BP1, PABPC1, and TIA1) in ascitic fluids and secretomes of cancer cells after chemotherapy." (PMID 38898005, 2024). "RBP Tia1 can interact with a variety of cancer-related mRNAs and is involved in multiple aspects of cancer development and progression, such as cancer cell proliferation, apoptosis, invasion, metastasis, angiogenesis, and immune escape." (PMID 37631029, 2023). "The regulatory mechanisms governing TIA1 expression and activity are complex and occur mostly at a post-transcriptional/translational level as previously suggested in other cancers." (PMID 35406476, 2022). "Worthy of note, TIA1 is the only RBP that suppresses the ability of cancer cells to escape immune response by enhancing NK cell cytotoxic activity; also, CPEB4 is the only RBP that promotes genome instability by influencing chromatin-remodeling." (PMID 31440515, 2019). "TIA1 inhibits both transcriptional and posttranscriptional events of many transcripts involved in cancer cell proliferation, apoptosis, angiogenesis, invasiveness, and metastasis as well as in immune evasion." (PMID 31440515, 2019). "For example, genes related to significantly enriched GO terms of cell adhesion and apoptosis, included COL4A3, PHLPP1, and TIA1, which were reportedly downregulated in cancer." (PMID 28903418, 2017). "AS of TIA-1 leads to expression of a truncated protein, called short TIA-1 (sTIA-1) in some cancer cells." (PMID 26273627, 2015). "However, the difference in the RNAs they interact with is reflected in the diseases that they are likely to be involved in, with TIA1 being involved in neuronal diseases and TIAR being associated more with types of cancer." (PMID 38534464, 2024). "Taken together, a better understanding of the mechanisms through which TIA1 increases or decreases gene expression in cancer may have great utility for the use of this protein both as a prognostic marker and as a potential drug target." (PMID 35163320, 2022). "Among them, TNRC6, DGCR8, C17ORF85, ZC3H7B, SFRS1 and TIA1, were obviously positively associated with XIST in ≥3 cancers; while eIF4AIII, FXR1, FXR2 and C22ORF28 were significantly negatively correlated with XIST in ≥3 cancers." (PMID 36212008, 2022). "Depending on the cancer type, TIA1 was reported to behave either as a TS or as an ONC." (PMID 35406476, 2022). "miR-19a binds directly to the 3′-UTR of TIA1 mRNA inhibiting TIA1 cancer suppressive features." (PMID 31440515, 2019). "Suppression of miR-19a activity could increase cellular levels of TIA1, therefore impairing cancer-related cellular processes." (PMID 31440515, 2019).
cancer (continued). "TIA1 is an important gene expression modulator, especially in cancers." (PMID 28257633, 2017). "Similarly, TIA1 protein overexpression was observed in most of cancer cells compared with normal mucosa." (PMID 26958940, 2016). "Previously, a few reports described the expression of TIA1 in human carcinomas." (PMID 26958940, 2016). "TIA1 and TIAR are mutated in several types of human cancers." (PMID 25741594, 2015). "TIA1 and TIAR genes are mutated and down-regulated in several types of human cancers." (PMID 25405991, 2014). "Overall, a significant difference in cancer-specific survival times was noted between the three groups with patients with higher amounts of CD8+/TIA-1+ TILs experiencing the most favourable outcome, followed by CD8+/TIA-1- cases and finally by CD8- patients (p<0.0001)." (PMID 21179245, 2010). "We confirmed that various spliceosomal proteins (TIA1, SFSF4, SYNCRIP, and SNU13) can be secreted from dying cancer cells and transferred into recipient cells using GFP- and RFP- fusion constructs and subsequent confocal microscopy and western blotting." (PMID 38898005, 2024). "Here, we show that TIA1 and TIAL1 bind to the same RNA binding sites and act redundantly over their RNA targets, as previously shown in different cancer cell lines." (PMID 37474714, 2023). "Among the RBPs identified, several were selected based on their detection intensity, relevance to extracellular vesicles, and reported connections to human cancer, including SRSF1, EIF3B, and TIA1." (PMID 32819370, 2020). "The role of TIA-1 and TIAR in cancer is still debated, because, in some studies, their depletion accelerates mitotic entry and proliferation, whereas, in others, they contribute to angiogenesis, tumor growth, and chemoresistance." (PMID 32882814, 2020). "Lymphocyte infiltration was evident even in the cancer nests, and the cells were predominantly CD3-, CD5-, CD7-, CD8-, and TIA1-positive T lymphocytes." (PMID 23642182, 2013). "In our analysis, the inflammatory cells consisted of a mixture of both T-cells and B-cells in lymphoid stroma, but the infiltrates in the cancer nests were predominantly CD8- and TIA1-positive T-cells." (PMID 23642182, 2013). "While TIA-1 can suppress the expression ofcancer-related genes such as COX-2, TIA-1's involvement in cancer is lesswell understood." (PMID 20157551, 2009). "TIA1 and TIAL1 were first described in cancer-infiltrating cytotoxic T cells." (PMID 37474714, 2023). "In this study, the patients with negative HLA-class 1 showed negative HLA-DR and a small number of CD8-positive, TIA-1-positive T cells, suggesting an impaired cancer immunity cycle." (PMID 35739295, 2022). "TIA1 is mostly considered as a tumor suppressor, due to its ability to reduce the translation of transcripts promoting carcinogenesis (e.g., cyclooxygenase-2, COX-2) in many cancers." (PMID 34502337, 2021). "However, we noticed that all SGs nucleators (TIA-1, TIAR, G3BP1, G3BP2, and CAPRIN-1) have an “enhancing” effect on cancer development properties, whereas USP10, a SGs inhibitor, has anti-cancer properties." (PMID 32882814, 2020). "In contrast, patients with negative HLA-DR tended to show a lower number of CD8-positive, TIA-1-positive T cells, or excluded or desert infiltration patterns, and did not respond to ICI therapy, suggesting an impaired cancer immunity cycle in these patients." (PMID 35739295, 2022).
infection (28 papers, 2008 to 2025). The state of being infected such as from the introduction of a foreign agent such as serum, vaccine, antigenic substance or organism. "Specifically, two of the genes: interleukin binding factor 3 (ILF3) and cytotoxic granule-associated RNA binding protein (TIA1), associated with robust T-cell response, were highly induced early in chimpanzees with self-limited infection." (PMID 18927617, 2008). "For example, poliovirus (PV) can inhibit the formation of SGs containing TIA1, which sequester translation initiation factors during infection." (PMID 35163320, 2022). "In Sindbis virus (SINV) infection, phosphorylation of eIF2α is required to initiate translation, and the formation of SGs, in which capsid proteins are recruited with the aid of TIA1, promotes protein synthesis." (PMID 35163320, 2022). "Nevertheless, a limitation of these studies is that mostly a single SG marker protein (TIA1) was used, precluding identification of compositional differences upon infection." (PMID 33996904, 2021). "The filamentous NP-associated structures increasingly co-localized with the Golgi and with the stress granule marker TIA-1 over the infection time course, suggesting a redistribution of these cellular organelles." (PMID 32605035, 2020). "Immunofluorescence microscopy revealed that, following infection, TIA-1 translocated from the nucleus to the cytoplasm and formed aggregates co-localizing with G3BP1 (first and second column), indicating that SGs are formed in RABV-infected cells." (PMID 27749929, 2016). "SGs containing IGF2BP1 protein induced by MuV infection (24 h post-infection) were only reduced by ~50% in TIA-1- or G3BP1-KD cells compared with control cells, although mRNA expression was decreased to a greater extent (data not shown)." (PMID 27560627, 2016). "Cells were harvested at 24 h post-infection and lysates analyzed by western blot to determine the expression of TIA-1, viral proteins and tubulin as control." (PMID 27749929, 2016). "The results for TIA-1 suppression using AdVs were consistent with those of a previous report indicating that TIA-1 is downregulated during the late phase of infection with wild-type adenovirus." (PMID 25275311, 2014). "Following infection with Sindbis vector, both eIF4E and eIF4G are contained within punctate structures and co-localize with TIA-1 indicating that they are located in stress granules." (PMID 20152035, 2010). "Virus context specific outcomes may be explained by different localisation of TIA-1 upon infection, and consequently, different interaction partners; however, further investigation is required to assess this hypothesis." (PMID 37606964, 2023). "Salmonella infection resulted in a transient induction of TIA1+ SGs at 1–2 h post infection (hpi)." (PMID 33996904, 2021). "During TGEV infection, the polypyrimidine tract-binding protein (PTB) is redistributed to the cytoplasm, associated with both TGEV gRNA and subgenomic mRNA (sgmRNA) and confined to TIA-1/TIAR aggregates." (PMID 27367717, 2016). "Interestingly, at a later time post-infection, aggregates containing viral RNA and TIA-1, but excluding the bona fide SG components eIF4G and PABP, are observed, suggesting that TIA-1 aggregation is unlinked from SG formation." (PMID 27367717, 2016). "The infection with Cricket paralysis virus (CrPV), a member of Dicistroviridae family, prevents the aggregation of Rox8 and Rin, Drosophila SG marker homologs of TIA-1 and G3BP-1, respectively, even in the presence of various stressor, such as arsenite, pateamine A or heat shock." (PMID 27367717, 2016). "Some RNA viral proteases, such as poliovirus proteases, actively bind and cleave stress granule proteins, including G3BP, PABP, and eIF4G, early during infection; nevertheless, stable stress granules containing TIA1 and positive-sense mRNAs form, promoting host cell shutoff." (PMID 24965446, 2014).